REN (renin)
Diseases named in the same sentence as REN in open-access papers (continued):
Sharing a sentence is not in itself a finding about the gene and the disease.
atherosclerosis (continued). "Moreover, Results obtained from our study showed that renin concentrations increased during chronic hypoxia and high-fat diet; this increase was less for hypoxia compared to atherosclerosis." (PMID 28740628, 2017). "Nevertheless, whether atherosclerosis itself leads to increased renin secretion and triggers renin–angiotensin system is yet to be elaborated." (PMID 28740628, 2017). "To explore the possibility that the renin associations with CVD and atherosclerosis burden was explained by a more frequent treatment with RAAS-inhibitors in subjects with more advanced disease we next analyzed subjects with and without RAAS-inhibitors separately." (PMID 27596252, 2016). "Notably, plasma renin levels were elevated also in non-T2D subjects with prevalent CVD and demonstrated significant associations with markers of atherosclerosis also in this group." (PMID 27596252, 2016). "First, it cannot be excluded that RAAS activation has no direct effect on atherosclerosis development in humans and that the association between renin and disease severity observed here is caused by association of renin with another atherogenic factor." (PMID 27596252, 2016). "This modulation of the renin-angiotensin system, in addition to decreasing blood pressure, improved the endothelial function and decreased inflammatory burden, thus limiting progression of atherosclerosis." (PMID 25807387, 2015). "Mitochondrial dysfunction is considered to contribute to disturbed glucose homeostasis in adulthood, which, in turn, promotes atherosclerosis through glycation, peroxisome proliferator-activated receptors, oxidative stress, inflammation, and renin-angiotensin system dysfunction." (PMID 23894450, 2013). "Angiotensinogen (AGT) constitutes a central component of the renin-angiotensin system that controls the systemic blood pressure and several other cardiovascular functions and may play an important role in atherosclerosis pathways." (PMID 23497386, 2013). "Extremely low salt intake also causes more long-term adverse effects, such as acceleration of atherosclerosis, as shown in a genetic model of atherosclerosis, the apoE−/−mouse: a low-salt diet stimulated the renin–angiotensin system and increased the size of atherosclerotic plaques in the aorta." (PMID 18535843, 2009). "In the present review, we focused on angiotensin-convertingenzyme (ACE) inhibitors, angiotensin II receptor blockers (ARBs), and renin inhibitors to update the direct activities of the renin-angiotensin system in inflammatory processes governing atherosclerosis." (PMID 19390623, 2009). "KEGG pathway enrichment of DEGs demonstrated that high expression of HMOX1 might have connections with cholesterol metabolism, phagosome, PPAR signaling pathway, TNF signaling pathway, and renin-angiotensin system, most of which were activated through the development of atherosclerosis." (PMID 35498043, 2022). "Secondary hyperparathyroidism activated renin-angiotensin-aldosterone system, elevated blood pressure, activated systemic inflammatory response and macrophage inflammatory response, promoted cholesterol accumulation in the vascular wall, and aggravated atherosclerosis." (PMID 36127705, 2022). "The observational Multiethnic Study of Atherosclerosis reported an independent association between plasma renin activity and cardiovascular outcomes in patients without previous CV events who had angiographically proven CAD or subclinical cardiovascular disease." (PMID 35187107, 2021). "Contrary to previous reports where the model of Ang II-dependent atherosclerosis was induced using exogenous administration of high doses of Ang II via minipumps, the 2K1C model is characterized by increased endogenous Ang II production in response to renal renin secretion stimulation." (PMID 30181481, 2018).
atherosclerosis (continued). "The higher prevalence of atherosclerosis in patients with CKD than in the general population may be caused by endothelial damage mediated by reactive oxygen species, activation of the renin-angiotensin-aldosterone system, and elevated levels of inflammatory mediators." (PMID 28957410, 2017). "Comparing our results obtained from atherosclerosis and atherosclerosis-hypoxia conditions on day 66, and considering the significant changes between two groups, it might be said that hypoxia condition promotes the secretion of renin." (PMID 28740628, 2017). "In addition, vascular smooth muscle cells’ proliferation, favoring the shift towards a synthetic phenotype, vascular re-modeling, and atherosclerosis through proteasome and renin–angiotensin system activation, may be promoted by a slight increase in SUA levels." (PMID 38921458, 2024). "Studies have shown that the renin–angiotensin–aldosterone system (RAAS) significantly impacts CVD, particularly atherosclerosis and hypertension." (PMID 39199169, 2024). "It is involved with lipid and atherosclerosis, HIF-1 signaling pathway, transcriptional misregulation in cancer, renin–angiotensin system, VEGF signaling pathway, and so on." (PMID 35873580, 2022). "KEGG enrichment analyses revealed multiple signaling pathways, including lipid and atherosclerosis, HIF-1 signaling pathway, renin–angiotensin system, and neutrophil extracellular trap formation." (PMID 35873580, 2022). "This study also showed that VDR-null macrophages exhibit increased renin-angiotensin system components, such as renin, angiotensinogen, or AT1R, and these animal subjects had significantly higher levels of atherosclerosis." (PMID 33572397, 2021). "For instance, it has been clearly demonstrated that the renin–angiotensin system (RAS) and the angiotensins, which are its mediators, promote atherosclerosis development and progression through local inflammation." (PMID 32485823, 2020). "In the kidney, uric acid is known to induce renal renin expression, enhance the activation of RAAS system, and initiate renal afferent arteriolar sclerosis, glomerular hypertrophy, and atherosclerosis." (PMID 29109738, 2017). "For atherosclerosis, pharmacological inhibition of AngII synthesis, through inhibition of ACE or renin, reduced the size of atherosclerotic lesions in several experimental models of atherosclerosis." (PMID 23236507, 2012). "Renin (REN), NT-proBNP, Natriuretic peptide B (NPPB), and proprotein convertase subtilisin/kexin type 9 (PCSK9) consistently emerged as the top contributors to the atherosclerosis-related, MR-derived, and whole proteome panels." (PMID 40585252, 2025). "Inducible PTC-specific deletion of AT1aR or ACE or increases of human AGT and renin in adult mice does not affect blood pressure and atherosclerosis in hypercholesterolemic mice." (PMID 37655218, 2023). "Furthermore, the components of the renin-angiotensin system, namely, angiotensin II (Ang-II), ACE2, and angiotensin-1-7 (Ang-1-7), have distinct roles in atherosclerosis." (PMID 37174317, 2023). "Additionally, the renin–angiotensin–aldosterone system (RAAS) is involved, resulting in elevated blood pressure, which together finally leads to atherosclerosis." (PMID 37629249, 2023). "Without adequate vitamin D, the renin–angiotensin–aldosterone system activates in an unopposed manner, and results in dysregulated cardiomyocyte proliferation, inflammation, and atherosclerosis progression." (PMID 34635717, 2021). "Taken together, these observations demonstrate that the renin associations with CVD and atherosclerosis burden observed in the present study is not due a more frequent treatment with RAAS-inhibitors in subjects with more advanced disease." (PMID 27596252, 2016). "Nevertheless, OPG could also promote atherosclerosis by stimulating systemic inflammation and the renin-angiotensin system (RAS) activation, which is one of the most important pathways leading to atherosclerosis." (PMID 27200369, 2016).
atherosclerosis (continued). "In this study, the effects of fistular onion stalk extract on the pathological features, circulating inflammatory cytokines, local renin-angiotensin-aldosterone system (RAAS) and signaling pathway activities were examined using an in vivo model of atherosclerosis." (PMID 25120600, 2014). "Third, presence of human AGT and renin in PTCs does not augment atherosclerosis in mice." (PMID 37655218, 2023). "Previous studies have shown that renin-angiotensin system antagonists could decrease cardiovascular events and mortality in stable CAD patients, and in the present study, the degree of atherosclerosis was significantly suppressed in mice after 7 months of ACEI administration." (PMID 36158825, 2022). "The present results suggest an involvement of renin gene expression in the NTN mouse independent of T2DM, chronic hypertension, and atherosclerosis, pointing to potential beneficial effects of GLP‐1R agonist treatment relevant for several forms of nephropathy." (PMID 34277961, 2021).
cardiac hypertrophy (169 papers, 2005 to 2026). "It is shown to play an important role in the development of cardiac hypertrophy, fibrosis and inflammation, all of which are pathophysiological mechanisms underlying HFpEF, likely through its link to the renin–angiotensin aldosterone system." (PMID 37233158, 2023). "It is generally recognized that TAC-induced cardiac hypertrophy is associated with increase of artery blood pressure, which is involved in activation of renin-angiotensin system (RAS)." (PMID 36195937, 2022). "Similar to CAMK2D, abnormal activation of the cardiac renin-angiotensin system is associated with cardiac hypertrophy." (PMID 32228691, 2020). "Consistently, at the molecular level, activation of the (P)RR by (pro)renin is associated with a detrimental transcriptional signature, e.g. linked to cardiac hypertrophy, cardiac and renal cell death." (PMID 24424509, 2014). "ISO infusion, which causes cardiac remodeling via direct effects on the heart in combination with increased renin levels caused equal cardiac hypertrophy and fibrosis in Wt and Tg mice." (PMID 24587131, 2014). "Recently, activation of ERK 1/2 was observed to be associated with cardiac hypertrophy and HF due to volume overload and these changes were attenuated by the blockade of the renin-angiotensin system." (PMID 27713345, 2010). "Todate, drugs targeting the renin-angiotensin system are the chief class of cardiovascular agents of special clinical utility in settings predisposing to cardiac hypertrophy based on the important role of angiotensin II in growth of cardiomyocytes." (PMID 15813973, 2005). "Reduced LRAT expression may lead to vitamin A deficiency, which can affect the renin–angiotensin system, promoting myocardial hypertrophy, ventricular fibrosis, and impaired cardiac function." (PMID 41300398, 2025). "Renin-angiotensin system activation causes renal insufficiency and myocardial hypertrophy, which may be attributed to an increase of E/e′ and explain our result." (PMID 36312236, 2022). "Therefore, development of RAS in both WT and db/db mice was associated with renovascular hypertension, increased plasma renin content, increased renal Ren1 expression, and cardiac hypertrophy." (PMID 24708836, 2014). "Here, we were able to confirm the previous data of our group that revealed that prorenin mediates pro-proliferative effects via the (P)RR-PLZF axis which is also consistent with a microarray analysis linking (pro)renin stimulation with a gene signature associated with cardiac hypertrophy." (PMID 24424509, 2014). "Another justification of repeated administration is the fact that adenosine reduces the release of noradrenaline, the production of endothelin and attenuates activation of the renin-angiotensin system, all of which are thought to cause cardiac hypertrophy and remodeling." (PMID 22462024, 2012). "Taking it a step further, Angiotensin II (Ang II) is known to be a degrading peptide of the renin–angiotensin system and is one of the most powerful stimulants inducing cardiac hypertrophy and fibrosis." (PMID 37219631, 2023). "We previously showed cardiac hypertrophy in a pregnancy-associated hypertensive (PAH) mouse model, in which an increase in angiotensin II (Ang II) levels was induced by human renin and human angiotensinogen, depending on pregnancy conditions." (PMID 36736425, 2023). "Our study suggests that Adra1a levels are regulated by renin-angiotensin system and that changes in Adra1a expression are involved in progressive cardiac hypertrophy in PAH mice." (PMID 36736425, 2023). "Both pathways can counteract neuroendocrine overactivation and inhibit the release of renin and aldosterone, resulting in vasodilation, inhibition of cardiac hypertrophy, reduction of cardiac preload, and improvement of ventricular remodeling." (PMID 36588555, 2022).
cardiac hypertrophy (continued). "Previous studies indicated that high-salt-induced ventricular hypertrophy in the hypertensive rat through various mechanisms including renin-angiotensin system probably by increased renin and aldosterone production." (PMID 36387352, 2022). "NAC supplementation decreased ROS levels, ameliorated this ultrastructure, inhibited expression of renin, Ang II and p16 protein and improved cardiac function and cardiac hypertrophy in hearts from Bmi‐1–/– mice." (PMID 35390228, 2022). "The renin-angiotensin system (RAS) is an important signal that regulates cardiac hypertrophy and involves atrial structural remodeling and cardiac hypertrophy of AF." (PMID 36159334, 2022). "The occurrence of cardiac hypertrophy is mostly considered to be related to neuroendocrine system dysfunction such as sympathetic nervous system excitation and renin-angiotensin-aldosterone (RAAS) system activation." (PMID 36247184, 2022). "In the course of disease progression, myocardial hypertrophy, fibrosis, and remodeling are involved, and a key mediator of this process is the activation of neurohormones, including regulators such as the renin–angiotensin–aldosterone system." (PMID 36435742, 2022). "For example, presumably through activation of FGFR1, the paracrine factor FGF2 promotes cardiac hypertrophy under conditions of excess catecholamine stimulation and renin-angiotensin system activation." (PMID 35513431, 2022). "Global VDR-knockout mice have been reported to have higher BP and to develop cardiac hypertrophy due to increased renin expression and subsequent RAAS activation." (PMID 36364874, 2022). "AngII is an important component of the renin–angiotensin system (RAS), and it can strongly constrict blood vessels, leading to cardiac hypertrophy by causing an increase in cardiac afterload." (PMID 36091816, 2022). "Increased renin and aldosterone action all promote cardiac hypertrophy and fibrosis, resulting in HF." (PMID 36143852, 2022). "As a consequence, signal transduction in the renin-angiotensin pathway was inhibited and resulted in vascular hypertrophy and abnormal blood pressure." (PMID 35910841, 2022). "Among signals modulating cardiac hypertrophy, the renin-angiotensin system (RAS) is essential and helps to maintain cardiovascular homeostasis." (PMID 36247184, 2022). "Angiotensin II, an important active peptide from the renin-angiotensin system, has been defined as a powerful stimulus to induce cardiac hypertrophy." (PMID 33510809, 2021). "Chronic activation of the myocardial renin-angiotensin system (RAS) and subsequent increased angiotensin II (Ang II) levels have been implicated in pathological cardiac hypertrophy." (PMID 34869682, 2021). "Meanwhile, aldosterone production is regulated by the renin–angiotensin system, and studies have shown that it has a direct effect on the heart, including recurrent cardiac hypertrophy and fibrosis, ultimately leading to cardiac remodeling." (PMID 34750628, 2021). "By activating the renin-angiotensin system, SUc promotes cardiomyocyte growth as well as water and salt retention, which can lead to myocardial hypertrophy." (PMID 33898356, 2021). "Contrastingly, the addition of high salt to a moderate fructose diet during pubescent, developmental years had lasting effects on cardiac and renal function evidenced by diastolic dysfunction, ventricular hypertrophy, and failed renin suppression." (PMID 34579006, 2021). "In turn, cardiac effects of hyperinsulinemia, including myocardial hypertrophy, can result among other factors from disturbed electrolyte balance, oxidative stress, enhanced sympathetic tone, and dysfunction of the renin-angiotensin-aldosterone system." (PMID 33221761, 2020). "It has been reported that sUA increases tumor necrosis factor-alpha, stimulates mitogen-activated protein kinases, and activates the renin–angiotensin system, all of which are known to promote cardiac hypertrophy." (PMID 33324684, 2020).